CTLA4 (cytotoxic T-lymphocyte associated protein 4)
Diseases named in the same sentence as CTLA4 in open-access papers (continued):
Sharing a sentence is not in itself a finding about the gene and the disease.
tumor (continued). "HRS cells and some tumor-associated macrophages (TAMs) are also positive for CD86, the CTLA-4 ligand, suggesting a role for the CTLA-4/CD86 axis in contributing to immune evasion." (PMID 37760478, 2023). "Here we show that blockade of PD-1 and CTLA-4 resulted in robust tumor suppression with functional augmentation of tumor-infiltrating CD4+/CD8+ T cells and an antitumor cytokine milieu." (PMID 37449205, 2023). "ICIs, such as anti-PD1, anti-PDL1, or anti-CTLA4, are engineered to express these antibodies in the tumor itself so that they can be less toxic than their systemic delivery." (PMID 37631987, 2023). "The therapeutic effect of anti-CTLA-4 antibodies in cancer can be attributed to selective depletion of tumour-infiltrating Tregs." (PMID 36319895, 2023). "Compared to monotherapy, the combination therapy resulted in increased survival of mice and smaller tumor volumes, indicating that local hyperthermia can enhance the efficacy of anti-CTLA-4 antibody treatment and improve the antitumor response." (PMID 37860188, 2023). "On the other hand, a triple combination of ISF35, anti-PD-1, and anti-CTLA-4 resulted in complete tumor eradication." (PMID 36604694, 2023). "CTLA-4 is expressed almost exclusively on T cells and binds to B7 molecules on antigen presenting cells (APCs) to promote tumor growth by inhibiting T cell immune response." (PMID 37305530, 2023). "The CTLA-4 pathway restricts immune responses in the early stages of T cell activation, while the PD-1/PD-L1 pathway mainly limits T cell activities in the tumor microenvironment." (PMID 37215995, 2023). "GM-CSF is another potent molecule that reduces tumor growth as effectively as anti-PD-L1 or anti-CTLA-4 antibodies." (PMID 37587450, 2023). "According to preliminary results, XmAb20717, which targets CTLA-4 and PD-1 simultaneously, was well-tolerated in patients with advanced cancer and had complete and partial responses in various tumor types." (PMID 37441075, 2023). "PD-1, CTLA4, CD96, and TIGIT are associated with each other in tumor immunity, which are candidates for immunotherapy." (PMID 36936375, 2023). "Antibodies against CTLA-4, PD-1 and PD-L1 can block the binding of CTLA-4 & CD80/86 on antigen presenting cells (APC) or the binding of PD-1 and PD-L1 on tumor cells, which can lead to binding of TCR and MHC causing T cell activation." (PMID 37064866, 2023). "Inhibition of checkpoint proteins such as PD-1 and CTLA4 triggers lymphocytic activation and enhances recognition and destruction of tumor cells." (PMID 36895912, 2023). "The patient displays high microsatellite instability (MSI) and tumor mutational burden (TMB) status and increased levels of CTLA-4 and PD-1 expression." (PMID 37783677, 2023). "In line with previously published reports, a clear dose-dependent relationship was observed between therapeutic efficacy and anti-CTLA4 dosage, with administration of a cumulative 10 mg/kg resulting in remarkable tumor inhibition." (PMID 37259163, 2023). "Studies showed that CTLA4 mRNA levels are upregulated in tumor tissues and correlate with a favorable prognosis." (PMID 36812479, 2023). "Rechallenging trials in mice treated with PTT and anti-CTLA-4 after 90 days of tumor-free survival revealed long-term immune protection against tumor recurrence, swiftly eradicating the rechallenging tumor." (PMID 36987269, 2023). "MHC expression on tumor cells from treatment-naive patients positively correlates with the clinical outcome and response to anti-CTLA-4, anti-PD-1, or their combination by recognizing tumor-specific antigens." (PMID 37033966, 2023). "Strategies to antagonise CTLA-4 as a means of increasing anti-tumour immunity eventually lead to US Food and Drug Administration (FDA) approval of ipilimumab for treatment of metastatic melanoma." (PMID 37345033, 2023).
tumor (continued). "In recent years, many findings have confirmed that immunosuppressive molecules such as cytotoxic T lymphocyte-associated antigen 4 (CTLA4), PD-1and its ligand PD-L1 are seen to be significantly overexpressed in the immune microenvironment of tumor patients." (PMID 37188271, 2023). "Dysfunction T cells reduced the production of tumor-killing cytokines and overexpressed the inhibitory receptors like PD-1, CTLA-4 and LAG3 as well as immunosuppressive enzyme CD39." (PMID 37312116, 2023). "We evaluated cellular immunity and alteration of microbiota induced by B. longum 420 and the synergistic effect of combining B. longum 420 with anti–PD-1 and anti-CTLA-4 antibodies in an RCC syngeneic mouse tumor model." (PMID 37340017, 2023). "By blocking the co-inhibitory receptor CTLA-4 using “checkpoint-blocking” antibodies, T cells can create a cytotoxic immune response in the tumor microenvironment (TME)." (PMID 38067379, 2023). "Through activating CTLA-4, NF-ĸB signaling is blocked and IL-2 production is inhibited, so anti-tumor immune responses by tumor cytotoxic T lymphocytes and NK cells become limited." (PMID 37735675, 2023). "It has been confirmed that various tumors escape T-cell killing by hijacking this mechanism, and antibodies directly targeting CTLA-4, PD-1, and PD-L1 have exhibited significant anti-tumor responses." (PMID 37386520, 2023). "Due to the low response rate to ICB in cancer treatment, identifying novel therapeutic targets to combine with CTLA-4 or PD-1/PD-L1 inhibitors is essential for enhancing anti-tumor effects." (PMID 38066642, 2023). "This is because blocking CTLA4 allows proliferation of tumor-specific T cells, which are most probably, also directed against other cancer testis antigens." (PMID 36527482, 2023). "By further combining with CTLA-4 blocking therapy, it efficiently controlled residual and metastatic tumor growth." (PMID 37064867, 2023). "Activation of checkpoint cascades, such as those controlled by PD-1 or CTLA-4, leads to tumor-specific T cell inactivation and immune evasion." (PMID 37316840, 2023). "These cells (present in the tumor stroma) usually express immune checkpoints such as PD-1 and CTLA-4, which bind to ligands on the surface of tumor cells (such as PD-L1 and CD28) and suppress the function of immune cells, especially T cells." (PMID 37790928, 2023). "T cell activity at an early stage is principally regulated by CTLA-4, whereas PD-1 mainly acts at a later stage in modulating the tumor microenvironment by restricting the action of T cells." (PMID 36829496, 2023). "Tumor growth of mice who received guadecitabine/anti-CTLA-4/anti-PD-1 (guadecitabine/ICBs; triple therapy) was compared to control or ICBs treated mice." (PMID 36934257, 2023). "Accordingly, anti-CTLA-4 treatment combined with BiLu moderately increased tumour killing and overall survival in mouse tumour models." (PMID 37599903, 2023). "Antibodies targeting immune checkpoints are contrived to enhance anti-tumor immunity by bypassing inhibitory pathways through the blockade of CTLA-4 or PD-1." (PMID 37762648, 2023). "Their interaction occurs at the lymph node, during the initial stage of the immune response, and when the B7 in the APC recognizing the tumor cell reacts with CTLA-4 in T cells; as a result, the immune response against tumor cells is suppressed." (PMID 36674491, 2023). "The tumor samples from these individuals were predicted to exhibit favorable immune responses to PD-L1 or CTLA4 inhibitors, or both." (PMID 37671160, 2023). "The authors used a combination immunotherapy cocktail consisting of PD-1 and CTLA-4 antibodies, Doxil nanomedicine, and tranilast to evaluate the efficacy on tumor growth." (PMID 37929901, 2023). "There was an upward trend of CD68+ macrophage and PD‐1+ and CTLA‐4+ tumor cells in the involved lymph nodes of R compared to C." (PMID 36751105, 2023).
tumor (continued). "The combination of CTLA-4 and PD-1 blockers has a synergistic effect on the activation of anti-tumor immune response." (PMID 37577750, 2023). "As pointed out above, the blockade of PD-1 and/or CTLA-4 enhances anti-tumor T cell-dependent immune response." (PMID 36765929, 2023). "CTLA-4 blockade has been shown to enhance T-cell activation and proliferation, including tumor infiltrating T-effector cells." (PMID 37304291, 2023). "It reactivates tumor monitoring functions of effector T cells by blocking immune checkpoints such as programmed cell death-ligand 1 (PD-L1) and cytotoxic T lymphocyte-associated antigen-4 (CTLA-4) and subsequently causes tumor cell death." (PMID 36926345, 2023). "The IPSs of patients in both risk groups indicated that the patients in the low-risk group had a better response to PD-1 and CTLA-4 blocking therapy, The same results were found for the TIDE calculation system based on tumor immune escape mechanisms." (PMID 37880277, 2023). "In this study, animals that responded to CTLA-4 therapy showed a homogeneous distribution of the anti-CD8+ PET signal throughout the tumor, whereas more heterogeneous infiltration of CD8+ T cells correlated with faster tumor growth and worse response." (PMID 36266600, 2023). "Nearly 50% of patients are treated with anti-cytotoxic T-lymphocyte associated protein 4 (CTLA4) and anti-programmed cell death protein 1 (PD-1) antibodies, leading to tumor regression and long-term long-lasting cancer control." (PMID 37207210, 2023). "Furthermore, tumor cells induced the differentiation of neighboring dendritic precursors to the Gr-1( +) conventional dendritic cell subpopulation and binding with cytotoxic T-lymphocyte-associated antigen 4 (CTLA-4), suppressing their proliferation and promoting the immune escape of cancer cells." (PMID 37978469, 2023). "The discovery of CTLA-4 and PD-1 checkpoints has prompted scientific researchers and the pharmaceutical industry to develop and conduct extensive research on tumor-specific inhibitors." (PMID 36674817, 2023). "Nevertheless, overexpression of immune checkpoints on tumor cells, such as PD-L1 and CTLA-4, impairs the tumor-killing potency of CD8+ T cells in TME." (PMID 37273004, 2023). "RT in combination with different forms of immunotherapy, such as anti-PD-1, and anti-CTLA4 antibodies, consistently improves local tumor control and leads to improved systemic tumor control (termed the abscopal effect); however, relapses often occur." (PMID 35794399, 2023). "One treatment strategy of the combination of immune CPIs, such as anti-PD-1 and anti-CTLA-4, has been instituted to bring immune cells into the tumor compartment and prevent them from being suppressed on arrival." (PMID 36891296, 2023). "TCR triggering and CD28 co-stimulation upregulate CTLA4 in T cells, and tumor cell-intrinsic CTLA4 upregulation can be induced by β-catenin signaling." (PMID 37197667, 2023). "Tumor immunotherapies, including chimeric antigen receptor T-cell immunotherapy and anti-PD-1/PD-L1/CTLA-4 monoclonal antibodies, have received a lot of focus as an integral aspect of combination therapy in recent years." (PMID 38152333, 2023). "Tumor-associated Tregs highly express immunosuppressive molecules, including FOXP3, CTLA-4, PD-1, CD39, ICOS, CD38, and IL32, as well as several specific surface signaling molecules (PD-L1, PD-L2, interleukin-1 receptor 2, and chemokine CCR8)." (PMID 37187731, 2023). "Altogether, it was shown that CTLA-4 blockades in each way, e.g., mAb or siRNA with the kind of NPs, can improve the anti-tumor efficacy of therapeutic strategies." (PMID 37735656, 2023). "To confirm the synergistic anti-tumor activity of adding the anti-CTLA-4 antibody to the combination of anti-PD-1 antibody and B. longum 420, we next performed further animal studies using the Renca-bearing BALB/c mouse RCC syngeneic tumor model." (PMID 37340017, 2023).
tumor (continued). "It has been clearly observed that blocking the immune checkpoint molecules PD-1 or CTLA-4 can generate strong anti-tumor responses but the majority of the patients are either refractory or develop resistance to these therapies." (PMID 37180119, 2023). "Low risk score indicated a higher PD1&CTLA4 immunophenoscore, higher TMB score, lower TIDE score and lower tumor escape score in HCC, suggesting a better immunotherapy response." (PMID 37725627, 2023). "The box plot indicated that expression of PD-1, PD-L1, and CTLA4 in tumor tissues was notably higher than in normal tissues." (PMID 37251440, 2023). "All animals bearing a single subcutaneous tumor that were treated with a single systemic dose of AU-011 combined with CTLA-4 or with PD-L1 together with LAG-3 antibodies had a CR." (PMID 36997666, 2023). "Patrycja Guzik and others explored the anti-tumor treatment of 177Lu nuclear medicine combined with an anti-CTLA-4 antibody." (PMID 36632233, 2023). "According to previous reports, the combined blockade of CTLA-4 and PD-1 amplifies anti-tumor T cell responses and provides synergistic activity." (PMID 37927462, 2023). "Regulatory T (Treg) cells and immunological checkpoints like CTLA-4 and PD-1 play a significant role in suppressing anti-tumor T-cell responses." (PMID 36674038, 2023). "Ipilimumab, an FDA-approved antibody targeting CTLA-4, seems to restore tumor immunity at the priming phase, whereas anti-PD-1/PD-L1 antibodies, such as pembrolizumab and nivolumab, restore immune function in the tumor microenvironment." (PMID 37046635, 2023). "The alternation of human commensal microbiota, such as Bifidobacteria and Bacteroides fragilis, induced anti-tumor immunity and potentiated efficacy of anti-PD-L1 or CTLA-4 blockade." (PMID 36999009, 2023). "The expression level of gene sets related to cytotoxic T cell activation (perforin, granzyme A, and granzyme B), costimulation (CD80 and CD86), and immune checkpoints (LAG3, CTLA4, PD-L1, and PD-1) was found to be increased in the tumor tissue." (PMID 37606040, 2023). "Separately, it has been documented that VISTA expression is strongly induced at the time of tumor progression following treatment with anti-PD-1 or anti-CTLA-4 therapy." (PMID 36891296, 2023). "In this study, OCLN expression was found to be significantly negatively correlated with PDCD1 and CTLA4 expression, which implicated the role of OCLN in regulating tumor immunology in KIRC." (PMID 37809090, 2023). "While CTLA-4 pathway inhibitors increase the infiltration and repertoire of tumor-specific T cells, PD-L1/PD-1 inhibitors work by preventing the inhibition of T-cell functions." (PMID 36810079, 2023). "Conversely, additional Treg depletion via anti-CTLA-4 in the A20 model enhances both the local and systemic anti-tumor effects of CpG + OX40." (PMID 37016127, 2023). "Immune checkpoint inhibitors target the PD-1 and CTLA-4 pathways to overcome a suppressive tumor microenvironment and potentiate endogenous anti-tumor T-cell immunity." (PMID 36911698, 2023). "They combined the mRNA vaccine with an anti-CTLA-4 monoclonal antibody to augment the anti-tumor effects." (PMID 37978542, 2023). "The therapy of immune checkpoint blockade (ICBs), which includes PD-1, PD-L1, and CTLA-4, has achieved remarkable success in the field of tumor immunotherapy." (PMID 37415161, 2023). "Anti-cytotoxic T lymphocyte antigen 4 (CTLA-4) therapy activates T cells and induces programmed death-ligand 1 (PD-L1) expression in tumor cells and TICs." (PMID 37373286, 2023). "The upregulation of immune checkpoint molecules, including CTLA-4, PD-1, and PD-L1, has been shown to contribute to tumor immune escape." (PMID 37968670, 2023). "Specifically, the abundance of α-SMA+ CAFs correlated with CD163+ MØs, in addition, we observed significantly positive correlations among α-SMA+ CAFs, CD163+ MØs and anti-tumor immune cells (i.e. CTLA4, FOXP3, CD4 and CD8 T cells)." (PMID 37254126, 2023).
tumor (continued). "They demonstrated a significant accumulation of the [64Cu]Cu-DOTA-anti-CTLA-4 mAb in the CT26 tumor, suggesting its potential as a non-invasive method to evaluate CTLA-4 expression." (PMID 38067379, 2023). "These are BsAbs targeting multiple immune checkpoint receptors (such as PDL1-41BB, PD1-LAG3, and PDL1- CTLA-4) or multiple antigens in the tumor cell (such as CD47- CD19 and CD19-CD22)." (PMID 38068428, 2023). "Tumor cells can exploit the CTLA-4 pathway, indirectly facilitating a suppressed immune environment favorable for tumor growth." (PMID 37987252, 2023). "Tumor-bearing LN (tbLN)-directed CTLA4 blockade generated robust anti-tumor response against local and systemic metastases, thereby improving survival." (PMID 37259163, 2023). "Upregulation of PD‐L1 or CTLA‐4 expression inhibits antitumor immune responses in the tumor microenvironment." (PMID 37291405, 2023). "Therapeutically we found that addition of anti-Ly6C to the combination of anti-PD-1/CTLA-4 was capable of complete tumor eradication." (PMID 37449205, 2023). "Although the expression of CTLA4 in NSCLC tumor tissues and cell lines has been reported, its expression in normal bronchial epithelium has not been evaluated." (PMID 37371664, 2023). "Through ex vivo modulation of the tumor microenvironment with CTLA-4 blocking antibodies, our group has shown similar broadening of the tumor-reactivity within the CD8+ compartment of TILs in ovarian cancer." (PMID 37359554, 2023). "This study provided the scientific basis for a clinical trial involving the combination of the CSC-DC vaccine and simultaneous PD-L1 and CTLA-4 blockades for improved tumor control in patients with cancer." (PMID 36900399, 2023). "Continuous HIV antigen stimulation persists even in patients receiving antiretroviral therapy, resulting in the tumor-specific CD8+ T cells becoming positive cells of CTLA-4 through the influence of continuously activated HIV-specific CD8+ T cells." (PMID 36923659, 2023). "There were significant positive correlations between TLT-1 and CTLA-4, PD1 (PDCD1), or TIM-3 in the tumor microenvironment, emphasizing the association of TLT-1 with CD8 T cell exhaustion in tumors." (PMID 36305874, 2023). "NK cells can be altered by tumor-derived EVs containing immune checkpoint molecules PD-1, PD-L1 and CTLA-4, which impair their cytotoxic activity by downregulating the expression of Natural Killer Group 2 Member D Protein (NKG2D) on the surface of NK cells." (PMID 37175226, 2023). "Previous reports have indicated the relevance of FcγR-dependent functions via., ADCC and ADCP in anti-CTLA-4 therapies, which contributes to antitumor responses in mouse tumor models." (PMID 37711295, 2023). "TMB has been reported to influence immunotherapeutic effectiveness across tumor types and can be used to predict the survival of diverse tumors with CTLA-4 or anti-PD-1 treatments." (PMID 38004399, 2023). "Although the clinical application of ICIs against CTLA-4 and PD-1 has shown significant anti-tumor response and improved the treatment of various cancers, irAE often occurs." (PMID 37936161, 2023). "This clearly indicates that a CTLA-4 blockade stimulated an anti-tumor response that is otherwise suppressed by Tregs." (PMID 37046685, 2023). "Immune checkpoints, including PD-1 and CTLA-4, are expressed on activated T cells, and T cell activation is inhibited when activated T cells bind to ligands on tumor cells/antigen-presenting cells." (PMID 38115906, 2023). "The discovery of immune checkpoints has led to the development of a new type of inhibitor (e.g., antibodies targeting the PD-1/PD-L1 axis and CTLA-4) that prevents the tumor from blocking the immune response." (PMID 38106674, 2023). "Given the high proportion of effector T cells within TIL we next used flow cytometry to assess the pattern of coexpression of checkpoint proteins PD-1, TIGIT, Tim-3, LAG-3, and CTLA-4 on T cells within the tumor microenvironment and peripheral blood." (PMID 36689623, 2023).